STAT3 (signal transducer and activator of transcription 3)
Diseases named in the same sentence as STAT3 in open-access papers (continued):
Sharing a sentence is not in itself a finding about the gene and the disease.
Hypertension (continued). "In particular, STAT3 could participate in favoring hypertension development during PE by increasing IL-17 levels, which serves an important role in hypertension." (PMID 39918020, 2025). "Network pharmacology screened 160 common targets of berberine and hypertension, among which STAT3 may play a key role." (PMID 41567631, 2025). "There was an interaction between the SOCS3, JAK2 and STAT3 genes and hypertension/triglycerides." (PMID 34991691, 2022). "The stimulation of JAK2/STAT3 pathway via Ang II has been shown in experimental studies, both in vitro and in vivo, and therefore play a vital role in the development of Ang II-dependent hypertension." (PMID 36324691, 2022). "Therefore, SIRT1‐dependent STAT3 acetylation and phosphorylation are critical to VSMCs proliferation, migration and phenotypic transformation during hypertension condition." (PMID 32627301, 2020). "Our data showed that IL-9 can significantly regulate Ang II-induced hypertension, which might be mediated by the STAT3 pathway." (PMID 32148441, 2020). "To investigate whether IL-9 is involved in hypertension through the regulation of inflammatory response, we detected STAT3 phosphorylation." (PMID 32148441, 2020). "Whether this action of Ang III to induce STAT3 occurs in peripheral cells, in particular, cells such as VSMCs that are known to contribute to the pathology of hypertension, is unknown and was the focus of this study." (PMID 31703282, 2019). "In this way, endothelial STAT3 may contribute to the impact of starvation or obesity on the cardiac remodeling that occurs with hypertension or ischemia." (PMID 31069236, 2019). "Interventions to enhance bioavailable NO, reduce IL-6 or hydrogen peroxide production or to inhibit STAT3 may have anti-inflammatory roles in hypertension and related conditions." (PMID 29800237, 2018). "In this regard, a targeted and inducible knockout model may be more desirable to assess the role of STAT3 in hypertension." (PMID 30619368, 2018). "JAK2/STAT3 signaling also is not required for blood pressure maintenance on LS diet, and appears uniquely linked to AngII hypertension, even at physiologic plasma AngII concentrations." (PMID 26486161, 2015). "Moreover, sera from patients with previous PE, current hypertension and carotid atherosclerotic plaques shows significantly lower STAT3(Y705) phosphorylation capabilities compared with healthy controls with previous uncomplicated pregnancies 8-18 years after delivery." (PMID 39918020, 2025). "Notably, while the pro-inflammatory role of STAT family members, such as STAT3, in hypertension has been reported, the role of STAT1/STAT2 in endothelial inflammation remains unclear." (PMID 40332339, 2025). "Moreover, in vivo studies demonstrated increased STAT3 activation in monocytes of hypertensive subjects as well as increased aortic and renal infiltration of monocytes and derived cells, with activated STAT3 in mice with experimental hypertension." (PMID 35694160, 2022). "Besides, STAT3 was significantly upregulated in the periodontitis group, while No3 knockout reduced its expression in the hypertension group and the periodontitis with hypertension group." (PMID 33448153, 2021). "We sought to determine the role of Ang III and its molecular target STAT3 on hypertension using VSMCs isolated from Wistar rats and ascertain whether differences exist in the actions of the peptide on this target in VSMCs isolated from the spontaneously hypertensive rat (SHR)." (PMID 31703282, 2019). "We also observed that mice homozygous for a STAT3 S727A mutation that impairs both genomic and non-genomic actions exhibited cardiac dysfunction and evidence of cardiac myocyte necrosis at an early stage of angiotensin II-induced hypertension." (PMID 26664907, 2015).
Hypertension (continued). "Evidence that STAT3 attenuates the contribution of NF-κB to hypertrophy and inflammation in the heart due to pressure overload would suggest that STAT3 activation could be exploited to protect the heart from hypertension-induced cardiac remodeling." (PMID 26664907, 2015). "Experiments showed that the AngII induced hypertension was relieved in the IL-6−/− mice, suggesting a key role IL-6 plays in the induction of hypertension depending on JAK2/STAT3 pathway in the kidney." (PMID 36195874, 2022). "Combined with protein interaction network analysis, the potential primary targets of berberine in treating hypertension may include AKT1, BCL2, EGFR, STAT3, and TNF." (PMID 41567631, 2025). "A study showed that the AngII-mediated activation of STAT3 could promote the transition of VSMC from a contractile to a synthetic phenotype, thus supporting the effect of VSMC on hypertension-induced angiopathy." (PMID 38166045, 2024). "In vivo studies demonstrated that humans with hypertension have increased intermediate and non-classical monocytes and that intermediate monocytes demonstrate evidence of STAT3 activation." (PMID 29800237, 2018). "Our findings suggest that STAT3 protects the heart from the harmful effects of hypertension, but the basis for this protection is not known." (PMID 27899891, 2016). "Because we proved that S3I-201 and STATTIC are not STAT3-specific, an additional role of other STATs in Ang II-induced vascular dysfunction and hypertension cannot be ruled out." (PMID 27166190, 2016). "The importance of STAT3 in protecting the heart from chronic stresses, such as hypertension, is not known." (PMID 27899891, 2016). "In this study, we assessed the importance of cardiac myocyte-specific STAT3 in maintaining the homeostasis of cardiac energy metabolism during hypertension using mice expressing a STAT3 in the heart lacking the domain important for both its mitochondrial and genomic actions." (PMID 27899891, 2016). "However, the importance of STAT3 to the heart in chronic stress, such as hypertension, is not known." (PMID 27899891, 2016). "The non-canonical actions of STAT3 involve gene induction by U-STAT3 that may sustain a hypertrophic and inflammatory gene program in the heart in response to hypertension; however, definitive evidence for that conclusion is lacking." (PMID 26664907, 2015). "In summary, our results revealed that the elevated plasma concentration of NPY during hypertension in pregnancy may induce VSMC proliferation mainly via Y5 receptor, which subsequently modulate STAT3 and c-Fos signaling pathways, and then induces vascular remodeling." (PMID 26131716, 2015).
ovarian tumor (43 papers, 2008 to 2025). "CD24 is linked to an increased metastatic and invasiveness potential in ovarian tumors and a shortened patient survival and is associated with signaling factors, such as Src kinase in lipid rafts microdomains, and requires STAT3." (PMID 37189618, 2023). "It is probable that B7-H4 is at least in part regulated by JAK/STAT3 signaling downstream of IL-6 and IL-10 receptors in ovarian tumor-associated macrophages, but this has yet to be formally tested." (PMID 26343197, 2015). "STAT3 is overexpressed in ovarian tumors and is associated with ovarian tumorigenesis." (PMID 22280969, 2012). "Silencing NEDD9 has been shown to reduce STAT3 activation, thereby suppressing ovarian tumor growth." (PMID 40362444, 2025). "This research confirmed that chronic stress downregulated HDC expression in ovarian tumor models, upregulating the expressions of IL-6, p-STAT3, and S100A9." (PMID 39720595, 2024). "We detected significantly higher levels of p-STAT3 in ovarian tumors from five out of six patients post PARPi therapy compared to the patient-matched tumor sections prior to PARPi administration." (PMID 34956861, 2021). "The Janus Kinase/Signal transducer and activator of transcription 3 (JAK/STAT3) pathway is one a major signalling pathway that is critical for ovarian tumour growth." (PMID 33809542, 2021). "According to a recent report, the IL-6-JAK/STAT3 interplay was found to correlate with increased ovarian tumor cell growth and resistance to chemotherapy." (PMID 34674640, 2021). "Our study also showed that ascites was associated with stage of OC, one probable mechanisms is that constitutive expression of STAT3 in malignant ascites plays a role in ovarian tumor progression and metastasis." (PMID 34476006, 2021). "Ablating STAT3 inhibited PARPi-resistant ovarian tumor cell growth and/or restored PARPi sensitivity." (PMID 34956861, 2021). "An enhanced expression of STAT3 has been reported in recurrent ovarian tumours extracted from metastatic ovarian lesions and ascites-derived tumours, compared to primary tumours and chemonaive ascites-derived tumours." (PMID 33023532, 2020). "At the same time, ovarian CAFs have been shown to be a major source of IL-6 in the TME, which activates STAT3 in ovarian tumor cells leading to cell proliferation and invasion." (PMID 33335857, 2020). "Altogether, our genome-wide, multi-omic analysis reveals a signature of STAT3 regulatory programs and uncovers new signaling networks of STAT3 promoting ovarian tumor growth, progression, and metastasis." (PMID 31534498, 2019). "Higher levels of STAT3 and p-STAT3 observed in patients' metastatic tumors versus primary tumors suggest a critical role of STAT3 in ovarian tumor progression/metastasis." (PMID 31534498, 2019). "Our results demonstrate that ruxolitinib, either alone or in combination with paclitaxel, can significantly inhibit STAT3 activation and ovarian tumor growth both in cells and in a mouse model." (PMID 29849942, 2018). "We and others have shown significantly enhanced expression of STAT3 in drug-resistant recurrent ovarian tumors derived from metastatic ovarian lesions and ascites-derived tumors, compared to primary tumors and chemonaive ascites-derived tumors." (PMID 29682172, 2018). "More interestingly, Nanog can form a complex with the p-Stat3, leading to Stat3-specific transcriptional activation in breast and ovarian tumor cells." (PMID 25879771, 2015). "Hypoxia induces expression and activation of STAT3, whereas oxygenation inhibits STAT3 activation and limits growth of human ovarian tumor xenografts in mice." (PMID 26343197, 2015). "A recent study has shown significantly enhanced activation of STAT3 sustained by infiltrating macrophages in drug-resistant recurrent ovarian tumors compared to the matched primary tumors." (PMID 24782986, 2014). "STAT3 mediated the multidrug efflux in breast and ovarian tumor cells, thus contributing to the resistance of CSCs." (PMID 24222909, 2013).
ovarian tumor (continued). "For the first time, our study demonstrates that DIM targets STAT3 to suppress the growth of ovarian tumor cells in vitro and in vivo." (PMID 22280969, 2012). "Previously published reports suggest that STAT3 is overexpressed in various tumors, including ovarian tumors." (PMID 22280969, 2012). "NCX-4040 can resensitize and potentiate the anticancer effect of cisplatin through downregulation of EGFR and STAT3 signaling in cisplatin-resistant human ovarian tumor xenografts in mice." (PMID 18302761, 2008). "Therefore, CD44 and STAT3 crosstalk deserves further investigation to identify promising novel strategies to sensitize ovarian tumors to treatment and prevent disease relapse." (PMID 33335857, 2020). "Collectively, these observations indicate that CD44 and STAT3 molecular cooperation deserves further attention and may be a promising clinical target to develop more effective therapeutics for the treatment of ovarian tumors." (PMID 33335857, 2020). "In addition, the concentration of IL-6 increases after platinum treatment of ovarian tumours, and IL-6 secreted by stromal fibroblasts activates STAT3 and enriches the numbers of ALDH+ CSCs in residual tumours." (PMID 33023532, 2020). "Whether this persistent STAT3 activation is responsible for enhanced expression of TIMP-2 in ovarian tumours or enhanced expression of TIMP-2 drives constitutive STAT3 activation remains to be determined." (PMID 33023532, 2020). "High level of Ror2 expression in platinum-resistant ovarian tumor was found to be coupled with upregulation of Stat3, suggesting that Stat3 might act as the signaling downstream of Ror2." (PMID 32216811, 2020). "Pre-clinical studies have suggested that targeting JAK/STAT3 could effectively suppress ovarian tumor progression and have therapeutic potential for treating advanced EOC." (PMID 31221207, 2019). "Thus, RAS and STAT3 consistently contribute to ovarian tumor growth, metastasis, and cisplatin resistance, but inversely regulate the MAPK- and PI3K/AKT-mediated ERS and autophagy." (PMID 31597912, 2019). "We have previously shown that ascites-derived ovarian tumor cells isolated from recurrent patients treated with chemotherapy have significantly higher expression of activated JAK2/STAT3 pathway compared to the tumor cells isolated from the ascites of chemonaive patients." (PMID 29682172, 2018). "However, chronic inflammatory stimuli and increased STAT3 activation have been shown to block cDDP-induced apoptosis, which impacts the course of ovarian tumor development and maintains the chemoresistance phenotype of EOC cells." (PMID 28388577, 2017). "We hypothesized that RA190 induced ER stress would inhibit Stat3 phosphorylation in MDSCs from ovarian tumor bearing mice." (PMID 27655678, 2016). "It will be important to determine whether STAT3 phosphorylation correlates with PD-L1 expression, and further determine whether treatment of ovarian tumor ascites CD14+ cells with small molecule inhibitors of STAT3 leads to reduced PD-L1 expression." (PMID 26343197, 2015). "Therefore, it is reasonable to postulate that CD44 and STAT3 not only mediate CAF-driven ovarian tumor stemness and chemoresistance within tumor cells, but also cooperate within CAFs themselves to support their cancer-promoting phenotype, which requires further investigation." (PMID 33335857, 2020). "Furthermore, we identified that compared with the vehicle treatment, BBI608 (a potent small‐molecule inhibitor of Stat3) reduced the expression of the proliferation marker Ki67 and increased the expression of cleaved caspase‐3 in tumour cells by inhibiting Stat3 activation in ovarian tumour cells." (PMID 31778258, 2020). "However, as both TIMP-2 and STAT3 are overexpressed in ovarian tumours, activated STAT3 and high TIMP-2 expression may play a dual role in maintaining in vivo ovarian tumourigenesis." (PMID 33023532, 2020).
ovarian tumor (continued). "Interestingly, recent report suggested that NFAT2 constitutive activation in transgenic mice also linked the microenvironment and the neighboring cells, as both tumor cells expressing NFAT2 and neighboring wild-type cells up-regulated c-Myc and STAT3 in spontaneous skin and ovary tumors." (PMID 27729023, 2016). "This may suggest a decreased role for STAT3 in the oncogenic function within ovarian tumors." (PMID 22174824, 2011). "Tumor-associated macrophages (TAMs) are the main population of immune cells in ovarian tumor stroma, and CD44 and STAT3 both significantly contribute to tumor promoting properties of the ovarian TME." (PMID 33335857, 2020). "In EOC patients, higher M2 TAM accumulation positively correlates with shorter survival rate and STAT3 activators IL-6 and LIF have been shown to drive M2 TAM phenotype switch in ovarian tumors." (PMID 33335857, 2020). "More importantly, CAFs also promote the CSC phenotype and chemoresistance development in ovarian tumor models and several studies have demonstrated that CD44 and STAT3 signaling pathways are involved in CAF-mediated therapy resistance." (PMID 33335857, 2020). "The xenograft model of the ovarian tumor made of OVCAR3 cells with STAT3 silencing grew slower than the control cells without treatment." (PMID 38067351, 2023). "Indeed, miR-551b upregulates STAT3 and c-KIT and enhances the resistance of ovarian tumor cells to anoikis." (PMID 27743201, 2016). "Overexpression of STAT3 was reported in stage III and IV ovarian tumors." (PMID 22280969, 2012). "We propose that the growth and invasive functions of TIMP-2 in ovarian tumour biology in vitro is MMP-dependent and are regulated by MT1-MMP, while the chemosensitivity aspect may be dependent on chemotherapy-induced activation of the STAT3 pathway." (PMID 33023532, 2020). "Ovarian tumor tissues have activated STAT3 in the nucleus and not in the cytoplasm." (PMID 23593315, 2013). "Around 86% of ovarian tumor tissues have activated STAT3 in the nucleus and not in the cytoplasm." (PMID 22280969, 2012). "Given that ovarian tumors express high levels of stem cell factor (KIT ligand), inhibition of the c-KIT/PI3K/Akt/mTOR pathway may reduce IDO expression, and may also limit signaling through CREB, STAT3 and HIF-1α, all of which potentially contribute to immune suppression and disease progression." (PMID 26343197, 2015).